MYCN (MYCN proto-oncogene, bHLH transcription factor)
Diseases named in the same sentence as MYCN in open-access papers (continued):
Sharing a sentence is not in itself a finding about the gene and the disease.
tumor (continued). "Both MYC and MYCN oncoproteins act on the mir-9-3 locus and cause activation of miR-9 expression in tumor cells." (PMID 21857930, 2011). "Kaplan–Meier survival curves were also performed with the low-risk subgroup defined by non-MYCN-amplified tumours of stage 4 <18 months including stage 4S." (PMID 21970883, 2011). "The characterization of the tumor at diagnosis is indispensable for deciding the treatment and includes the evaluation of risk factors such as MYCN amplification status, hystotype, tissue markers, and chromosomal rearrangements." (PMID 20624283, 2010). "MYCN amplification in NB increases risk for tumor spread to the liver, which in turn significantly decreases 3 year event-free survival in the patient group of INSS stage 4 and age over 1 year." (PMID 19284605, 2009). "MYCN amplification has been shown to be strongly associated with rapid tumour progression and poor prognosis in patients of all ages, with any stage of disease." (PMID 19401703, 2009). "Spitz reported that 6% of tumours displayed MYCN gain and this MYCN gain was associated only with a poor outcome in localized or 4s NB cases." (PMID 16670717, 2006). "Further investigations of the mechanism(s) underlying MYCN-driven tumor development can shed light on the regulation of MYCN and its specific upstream and downstream signaling pathways, which will provide more opportunities to develop therapeutic strategies for MYCN-driven cancer." (PMID 39802403, 2025). "MYCN-driven high-risk NBs may enhance the eIF4F translation machinery to sustain tumor growth and metastasis, and elevated expression of eIF4A1, eIF4E1, and eIF4G1 correlate with poor prognosis." (PMID 41279557, 2025). "MYCN amplification has been implicated in many studies about the cold tumor phenotype in NB." (PMID 40082458, 2025). "MYCN further promotes immune evasion by inducing infiltrating immunosuppressive cells, including T regulatory cells, through chemokine-like factor upregulation, tumor-associated macrophages, and cancer-associated fibroblasts." (PMID 40507292, 2025). "Since MYCN amplification also strongly correlates with 1p36 loss in NB tumors, 1p36 genes could also be contributing to the cold tumor phenotype." (PMID 40082458, 2025). "Notably, a newly published study has shown that high-risk tumours with MYCN amplification respond better to treatment regimens involving JNK-independent drugs, confirming that the JNK pathways are significantly silenced in this subtype." (PMID 41465323, 2025). "MYCN amplification is linked to tumor metastasis, poor prognosis, and treatment challenges." (PMID 40104501, 2025). "An association (CS < 0.9) with TMM positive or MYCN type class seemed to contain supportive information on tumour biology associated with worse prognosis, and in line with this an association with TMM negative had a worse prognosis than those that classified (CS ≥ 0.9) into TMM negative subclass." (PMID 40713849, 2025). "MYCN amplification is present in 30% of NB cases and is associated with aggressive tumor growth." (PMID 40004600, 2025). "MYCN amplification is associated with tumor aggressiveness through multiple pathways." (PMID 40429864, 2025). "Moreover, MET controls tumour and 3D spheroid tumour growth and its expression is associated with poor prognosis, tumour progression, relapse, and elevated levels of MYCN in patients." (PMID 41511287, 2025). "To uncover how far collateral vulnerabilities can be directly induced by coamplified passenger genes, we performed a proof-of-principle analysis in models with MYCN amplifications, which are frequent in many tumor entities and are often associated with high-risk disease and poor therapeutic outcome." (PMID 38197697, 2024).
tumor (continued). "As expected, Nudt1 knockout significantly increased the expression of phosphorylated γH2AX in sympathetic ganglia associated with elevation of cleaved-Caspase 3, corroborating that NUDT1 deletion caused overwhelming DNA damages and cell death in MYCN-driven tumor contexts in vivo." (PMID 38493213, 2024). "Furthermore, the mRNA level of MYCN was observably higher in HCC tissues than in non‐tumor tissues, and a high MYCN level in HCC patients was clearly associated with a low survival probability." (PMID 39248163, 2024). "In addition, a combination of BRD4 and PLK1 inhibitors showed synergistic anti-tumour effects in paediatric tumour models including RMS that is associated with MYCN-driven gene expression." (PMID 38191874, 2024). "Moreover, data suggest that MYCN amplification, a feature associated with tumours with an unfavourable prognosis, results in increased resistance to oxidative stress." (PMID 38542729, 2024). "Six genes CCSER2, AGAP11, IFIT2, PAPSS2, PCGF5, and NUDT9P1 were observed to have potential NB tumor suppressor activity since their low expression was associated with poor survival even after correction for confounding by other prognostic factors (MYCN status, age at diagnosis, stage of disease)." (PMID 37046696, 2023). "In addition, some miRNAs have been shown to play a role in influencing tumor progression by regulating tumor-associated protein MYCN." (PMID 37426487, 2023). "However, only a limited number of MYCN-regulatory proteins associated with tumor initiation and progression have been elucidated." (PMID 37274289, 2023). "Thus, the inhibition of p300 in MYCN-amplified NBs is associated with a less malignant phenotype, less aggressive tumor behavior, and lower protein levels of N-Myc." (PMID 36708875, 2023). "Ferroptosis is associated with the MYCN gene and might be closely related to shaping the tumor immune microenvironment." (PMID 37521469, 2023). "Furthermore, the weight of tumor plus kidney exhibited a consistent result with subcutaneous xenograft that BAP1 depletion markedly reduced the weight but overexpression of MYCN partially rescued BAP1 depletion-caused weight reduction." (PMID 37543638, 2023). "Therefore, overexpression of MYCN is associated with poor prognosis, advanced stage of disease, rapid tumor growth and metastasis." (PMID 37274289, 2023). "Tumour 1 was a metastatic relapse sample from a patient with non-MYCN amplified, high risk, NB." (PMID 37958407, 2023). "A signature constructed the six MYCN-amplified differential genes and aging-related genes can be used to predict the prognosis of NB better than using each high-risk gene individually and to evaluate immunosuppressed and aging tumor microenvironment." (PMID 38035110, 2023). "Patient prognosis is currently based on a combination of clinical, histopathological and biological features such as age at diagnosis, stage of the disease, MYCN amplification, loss of heterozygosity for chromosome 1p and 11q (LOH1p and LOH11q), tumor ploidy established at diagnosis." (PMID 35756625, 2022). "MYCN amplification and overexpression in NB is associated with increased proliferation and enhanced malignant potential, while knockdown of MYCN has been shown to result in tumor growth arrest and apoptosis in NB." (PMID 35018218, 2022). "MYCN is an identified driver and reliable genomic hallmark of aggressive tumor behavior." (PMID 35820898, 2022). "Indeed, aberrant overexpression of the MYCN oncogene is associated with poor prognosis, tumor aggressiveness, and resistance to chemotherapy." (PMID 36551697, 2022). "Also, here a unifying picture captures additional aspects of the tumor evolution with a MYCN-amplification in the stem and a subclonal NRAS mutation." (PMID 34545199, 2021). "One key driver of NEPC is N-Myc, encoded by MYCN, which is required for PCa tumor maintenance." (PMID 33810413, 2021).
tumor (continued). "Since ATRX loss of function and MYCN amplification are reported to be mutually exclusive, and 11q deletion is very rarely observed in MYCN-amplified tumours, we propose PARP and ATR inhibitors may be beneficial to a large subset of high-risk NB patients." (PMID 34944835, 2021). "However, this is the first study to further analyze NKT expression in the NBL TME according to the tumor’s MYCN status, demonstrating that fewer NKTs were associated with worse EFS and OS in MYCN-non-amplified NBL and with worse OS in MYCN-amplified NBL." (PMID 33668573, 2021). "However, FISH of those tumours showed heterogeneity in MYCN amplification and also in loss at 1p (cases 53 and 54) or loss at 11q (case 58)." (PMID 34680323, 2021). "Future studies could also investigate which organs are infiltrated by tumor in order to determine which structures are associated with decreased survival and histopathology such as MYCN amplification and high MKI." (PMID 33314708, 2021). "Risk score, age, tumor histology, and MYCN status were parameters included in the nomogram." (PMID 34950701, 2021). "In addition, consistently observed high-risk biological factors (MYC amplification (~5% of tumours), MYCN amplification (~10%)) were identified." (PMID 34885186, 2021). "In addition, association of MYCN amplification with advanced tumor stage and disease progression in NBL has long been known." (PMID 33668573, 2021). "Approximately 20% of the high-risk NB tumours present with amplification of MYCN." (PMID 32714600, 2020). "Additionally, a maximum primary tumor diameter > 13.20 cm and MYCN gene amplification are two independent risk factors for high-risk NB tumor rupture." (PMID 32293329, 2020). "In addition, NB tumours with MYCN amplification or ATM deficiency have been shown to have increased sensitivity to single agent olaparib treatment." (PMID 32354033, 2020). "In the multivariate logistic regression analysis, a maximum primary tumor diameter > 13.20 cm and MYCN gene amplification were two independent risk factors for high-risk NB tumor rupture, with adjusted odds ratios (ORs) of 6.401 (1.986, 20.626) and 7.874 (2.520, 24.603), respectively." (PMID 32293329, 2020). "Furthermore, they found that higher levels of SGOC gene expression are significantly linked to tumour stage advancement and unfavourable prognosis in MYCN-amplified NB patients." (PMID 32034121, 2020). "Similarly, PIM inhibition has previously been suggested as a therapeutic option in MYC/MYCN‐associated tumor types." (PMID 31310053, 2019). "We confirmed MYCN amplification, a NB hallmark related to poor outcome of the HR patients in patients older than 1 year, 1p deletion, 11q loss and 17q gain, that occurs in about 50% of the tumours." (PMID 31638925, 2019). "More specifically MYCN is an oncogene and tumor driver in high-risk poor prognostic NB." (PMID 31455317, 2019). "lnc-GOLGA61-1 is upregulated in tumor samples harboring an ALK mutation or a MYCN amplification." (PMID 30952905, 2019). "Thus, MYCN amplification is associated with advanced stage, rapid tumor progression, and poor prognosis." (PMID 30691436, 2019). "MYCN amplification is also responsible for the loss of chromosomal 1p36 heterozygosity, which downregulates the expression of miR-340, a miRNA that possesses tumour suppressant properties, and is upregulated by demethylation of an upstream genomic region." (PMID 29315268, 2018).
tumor (continued). "Additionally, ODC1 itself has been shown to be amplified in ~6% of high-risk tumors along with MYCN and associates with exceptionally poor tumor survival (and unpublished data)." (PMID 29799508, 2018). "MYCN amplification occurs in 20% of cases overall, rising to 50% in high-risk tumours." (PMID 29642598, 2018). "Thus, MYCN amplification seems to be the major cause of sporadic NB and other mutations support tumor aggressiveness." (PMID 29371588, 2018). "In addition to RB1 as the rate-limiting step for tumor initiation, there are multiple genes (oncogenes and tumor suppressor genes) that undergo mutations, such as MYCN gain, loss of 16q, etc., thereby promoting tumorigenesis." (PMID 29162051, 2017). "In agreement with this, our previously reported ALKR1275Q knock-in and MYCN transgenic compound mice revealed that the co-operation of ALK mutation and MYCN overexpression results in impaired normal extracellular matrix/basement membrane integrity and enhanced tumor growth and dissemination." (PMID 29296183, 2017). "In 2008, the INRG group implemented a pretreatment risk stratification considering age, MYCN amplification, histological tumor grade, Image Defined Risk Factors and 11q deletion to classify NB patients into very low-, low-, intermediate- and high-risk patients." (PMID 28778185, 2017). "Thus, RA and KGN combination treatments represent a novel therapeutic option with potential for targeting high-risk MYCN-amplified tumours." (PMID 28187790, 2017). "Indeed the focal pattern was significantly associated with amplification of MYCN, which is considered a major tumour-driving gene." (PMID 25267348, 2015). "Of interest, several data indicated that MYCN is functionally linked with tumor angiogenesis." (PMID 26633716, 2015). "Also, NBAT1 shows lower expression in all high-risk tumours including both the MYCN and 11q-subtypes, which constitute a major fraction of high-risk NB tumours." (PMID 26087192, 2015). "Among the abnormal chromosomal and genetic features associated with this class of tumours is the amplification of the proto-oncogene MYCN, a member of the MYC gene family, which encode transcription factors involved in the regulation of cell proliferation and growth." (PMID 24965943, 2014). "Presence of MYCN amplification is associated with adverse outcome and tumour progression." (PMID 24679140, 2014). "This remains entirely speculative but may offer a possible explanation regarding the association of MYCN amplified tumours with adverse outcome." (PMID 24679140, 2014). "There are a lot of risk factors which are believed to have a role in disease progression, such as age at the time of initial presentation, tumor stage, histology and ploidy of tumor, and cytogenetic aberrations including MYCN amplification, loss of heterozygosity of 1p and 11q, and 17q gain." (PMID 25254086, 2014). "Tumor cell lines from poor prognosis, high-risk patients contain a number of genetic alterations, including amplification of MYCN, 1pLOH, and unbalanced 11q or gains of Chr 17 and 7, and exhibit uncontrolled growth and an undifferentiated phenotype in in vitro culture." (PMID 23373009, 2013). "DFMO treatment leads to the accumulation of the cyclin-dependent kinase inhibitor p27Kip1 protein and causes p27Kip1/Rb-coupled G1 cell cycle arrest in MYCN-amplified NB tumor cells through a process that involves p27Kip1 phosphorylation at residues Ser10 and Thr198." (PMID 23440295, 2013). "Amplification of MYCN is associated with rapid tumor progression and poor prognosis." (PMID 23226679, 2012).
tumor (continued). "Finally, we investigated the prognostic value of miR-487b and miR-410 expression levels in the subgroup of low-risk patients as defined by non-MYCN-amplified stage 1, 2 and 3 tumours." (PMID 21970883, 2011). "Many prognostic studies have identified several tumor markers associated with overall or disease-free survival, including MYCN copy number, tyrosine kinase A (TrkA) expression level, ploidy, and deletion or loss of heterozygosity of chromosome 1p and gain of chromosome 17q." (PMID 24281085, 2010). "However, in high-risk or MYCN-amplified tumors, aberrant Wnt signaling may promote tumor development and stemness." (PMID 40429864, 2025). "MYCN-amplified (a proto-oncogene that is associated with poor prognosis in NB) NB cells have been shown to play an important role in tumor progression and development by secreting some exosomal miRNAs and result in changing the tumor environment in favor of tumor growth." (PMID 35371984, 2022). "However, DMBA-induced elevated expression of MYC and MYCN oncoproteins cause an increase of miR-9 expression in tumor cells, which (this time via a positive feedback mechanism, supporting oncogenes)–through the amplification of E-cadherin–induces further increase of C-MYC expression." (PMID 33539381, 2021). "In addition to MYCN a plethora of segmental chromosome alterations (SCAs) are associated with poor prognosis in NB, notably deletion of 1p and 11q, and gain of 17q; most high-risk tumours carry at least one such alteration." (PMID 31088252, 2019). "Furthermore, a study evaluating the prognostic significance of different molecular markers (including 1q gain, 1p and 16q losses, and MYCN gain) in a large case series of WT showed that, besides tumor stage and high-risk histology, only 1q gain is an independent predictor of event-free survival." (PMID 29255497, 2017). "The recent finding that MYCN overexpression induces caspase-3 in zebrafish neuroblasts raises the possibility that oncogene activity may be an important cause of cell death in SAPs and in tumor cells." (PMID 26222553, 2015). "Therefore, the hypothesis has been raised that blocking MYCN expression or its action could lead to less aggressive tumours, and lead to new therapies for high-risk patients." (PMID 24679140, 2014). "MYCN-driven oncogenesis promotes tumor progression by suppressing apoptotic signaling and enhancing survival pathways, including autophagy-a key mechanism underlying resistance to chemotherapy and immunotherapy." (PMID 41750126, 2026). "Our findings gain credence from earlier studies emphasizing the consequences of MYCN inactivation leading to sustained tumor regression." (PMID 41539997, 2026). "MYCN oncogene amplification is a major driver of tumor aggressiveness and poor prognosis and is inversely correlated with immune infiltration in the tumor microenvironment (TME)." (PMID 41936749, 2026). "MYCN phosphorylation and expression was decreased in tumor lysates from animals treated with ATUX-1215 or ATUX-5800." (PMID 41539997, 2026). "Collectively, exosome-based strategies represent a paradigm shift in formulating combination therapies, offering a multifaceted approach to target MYCN amplification, inhibit autophagy, induce apoptosis, and modulate the tumor-microbiome axis." (PMID 41750126, 2026). "In recent decades, numerous studies have identified a number of important factors affecting prognosis and tumor progression, such as age, MYCN amplification, 11q deletion and tumoral heterogeneity." (PMID 41602364, 2026). "Tumor growth decreased in animals treated with ATUX-1215, and analysis of tumor specimens confirmed decreased MYCN expression." (PMID 41539997, 2026). "Analysis of patient data revealed reduced expression of PKA pathway genes in MYCN-amplified tumours." (PMID 41876468, 2026).